SDR16C5 (short chain dehydrogenase/reductase family 16C member 5)
Description:
Oxidoreductase with strong preference for NAD. Active in both the oxidative and reductive directions. Oxidizes all-trans-retinol in all-trans-retinaldehyde. No activity was detected with 11-cis-retinol or 11-cis-retinaldehyde as substrates with either NAD(+)/NADH or NADP(+)/NADPH.
Synonyms: EPHD-2; RDH-E2; retSDR2; RDHE2; RDH#2
Tractability: Antibody: its Gene Ontology location is reachable by antibodies, with high confidence; UniProt predicts a signal peptide or a membrane-spanning region. PROTAC: ubiquitination databases record sites on it.
Gene: Protein-coding gene on chromosome 8 (56,300,005 to 56,320,776, reverse strand). Ensembl gene ENSG00000170786.
Subcellular location: Endoplasmic reticulum membrane
Pathways (Reactome):
Signal Transduction: RA biosynthesis pathway
Gene Ontology:
Molecular function: all-trans-retinol dehydrogenase (NAD+) activity; DNA-binding transcription factor binding; protein binding; RNA polymerase II-specific DNA-binding transcription factor binding; transcription corepressor activity
Biological process: keratinocyte proliferation; negative regulation of gene expression, epigenetic; negative regulation of transcription by RNA polymerase II; retinal metabolic process; retinol metabolic process
Cellular component: chromatin; endoplasmic reticulum; endoplasmic reticulum membrane; nucleus; plasma membrane; transcription repressor complex; lipid droplet
Genetic constraint (gnomAD): Loss-of-function variants: 11 observed, 15.18 expected, observed/expected ratio (o/e) 0.72, 90% interval 0.46 to 1.2. The upper end of that interval is the gene's LOEUF score, 1.2, which puts it in group 5 of 6, group 1 being the genes least tolerant of losing a copy. Missense variants: 272 observed, 261.76 expected, observed/expected ratio (o/e) 1.04, 90% interval 0.94 to 1.15. Synonymous variants: 98 observed, 97 expected, observed/expected ratio (o/e) 1.01, 90% interval 0.86 to 1.2.
Homologues: Orthologues: macaque SDR16C5 (92% identical), chimpanzee SDR16C5 (92% identical), rabbit SDR16C5 (84% identical), rat Sdr16c5 (82% identical), mouse Sdr16c5 (80% identical), dog SDR16C5 (77% identical), guinea pig SDR16C5 (77% identical), pig SDR16C5 (75% identical), tropical clawed frog sdr16c5 (62% identical), zebrafish sdr16c5b (60% identical), zebrafish sdr16c5a (55% identical). Paralogues in human: RDH10 (44% identical), HSD17B11 (41% identical), HSD17B13 (39% identical), DHRS3 (34% identical), HSD17B6 (26% identical), HSD17B4 (26% identical), RDH5 (24% identical), RDH16 (24% identical), SDR9C7 (24% identical), RDH11 (23% identical), DHRS9 (23% identical), RDH12 (23% identical), and 13 more.
Diseases named in the same sentence as SDR16C5 in open-access papers:
SDR16C5 is named in the same sentence as 2 diseases in open-access papers, as found by Europe PMC text mining. Sharing a sentence is not in itself a finding about the gene and the disease.
SDR16C5 shares sentences with these, for which no sentence is quoted: pancreatic cancer (1 paper); polycystic ovary syndrome (1).